BCL2 (BCL2 apoptosis regulator)
Diseases named in the same sentence as BCL2 in open-access papers (continued):
Sharing a sentence is not in itself a finding about the gene and the disease.
synovial sarcoma (continued). "Phosphorylation of BCL-2, deactivating this important anti-apoptotic regulator, is also found to occur following the quisinostat/proteasome inhibitor combination treatment, resulting in a pro-apoptotic shift not seen with doxorubicin treatment in synovial sarcoma." (PMID 28056055, 2017). "Result came with the finding of tumor being diffusely positive for TLE1, CD56, and BCL2 and negative for STAT6, CD34, and Desmin, suggestive of synovial sarcoma." (PMID 40747128, 2025). "In contrast, the atypical synovial sarcoma SW982, which expresses neither the SS18-SSX oncogene nor high levels of BCL-2, was resistant to the combination." (PMID 34065859, 2021). "While Bcl-2 is negative, CD34 and STAT6 are negative in synovial sarcoma and can thus aid in differentiating from SFT." (PMID 32566457, 2020). "Immunohistochemically, synovial sarcomas show immunoreactivity for cytokeratins, EMA, S-100 protein, are positive for Bcl-2, O-13, Actin and negative for CD34 and Desmin." (PMID 20062586, 2009). "In our case, immunohistochemistry confirmed the diagnosis of monophasic synovial sarcoma, with the tumor cells being non-reactive for S-100, Smooth Muscle Actin (SMA), and neurofilament, but positive for TLE1, BCL2, and CD99, which are indicative of this type of sarcoma." (PMID 39364429, 2024). "In common with other synovial sarcomas, the immunohistochemical staining demonstrated some typical findings of synovial sarcoma: the tumor cells were positive for vimentin and CD99, but negative for CD34, Bcl-2, alpha smooth muscle actin, desmin, and S-100 protein." (PMID 24969223, 2014). "All synovial sarcomas were negative for CD34 and positive for both bcl2 and CD99." (PMID 24131748, 2013). "Therefore, although the “gold standard” for synovial sarcoma is molecular testing, TLE1-targeted therapeutics could be used to selectively treat synovial sarcoma without damaging host tissue and could be a useful immunohistochemical marker in combination with CD37, CK7, EMA, BCL2, and MIC2." (PMID 27852056, 2017).
myeloid leukemia (45 papers, 2002 to 2025). A clonal proliferation of myeloid cells and their precursors in the bone marrow, peripheral blood, and spleen. "Mcl-1, a member of the Bcl-2 anti-apoptotic protein subfamily, was first identified in the ML-1 human myeloid leukemia cell line in 1993." (PMID 35632731, 2022). "Etoposide treatment also caused a significant decrease of the anti-apoptotic factor BCL2 gene expression and protein levels in THP-1 myeloid leukaemia cells, when compared to the vehicle control (P ≤ 0.05)." (PMID 35614109, 2022). "In mammals, cytokines have been reported to impinge on apoptosis by affecting the expression levels of Bcl-2 and Bcl-xL in myeloid leukemia cells." (PMID 35121747, 2022). "Interactions between GSK-3 and the pro-apoptotic Bim molecule have been shown to increase the pro-apoptotic effects of BCL2/BCLXL inhibitors in human myeloid leukemia cells which were also treated with PI3K inhibitors." (PMID 33917370, 2021). "These promising findings led to the development of clinical trials investigating a BCL-2-targeting BH3 mimetic in combination with azacitidine in myeloid leukemias." (PMID 33637708, 2021). "This derivative also displayed cytotoxic properties (IC50 values ∼1 μM) in the human myeloid leukemia U-937 cell line overexpressing human Bcl-2 (U-937/Bcl-2) via cell cycle progression arrest at the G2-M phase and induction of apoptosis." (PMID 30141353, 2018). "Mcl-1, which was first identified in human myeloid leukemia cell line ML-1, structurally resembles other anti-apoptotic Bcl-2 proteins." (PMID 26927133, 2016). "For example, in an in vitro study of human myelogenous leukemia cells, ajoene was shown to activate caspase-3 and cleave Bcl-2." (PMID 26927133, 2016). "The purpose of this study is to analyze the expression pattern of miR-29a/29b and its target genes Mcl-1 (myeloid cell leukemia sequence 1) and B-cell lymphoma 2 (Bcl-2) in myeloid leukemia." (PMID 25006537, 2014). "Down-regulated miR-29a and miR-29b, and accompanying up-regulated Bcl-2 and Mcl-1 are the common feature in myeloid leukemias." (PMID 25006537, 2014). "According to different studies in tumor cells, the effects of α-linolenic acids in myeloid leukemia seemed to be directly related to PI3K pathway and Bcl-2 inhibition associated with caspase activation." (PMID 21991326, 2011). "Indeed, a recent study reported that YBX1 is required for maintaining myeloid leukemia cell survival by regulating BCL2 stability in an m6A-dependent manner." (PMID 35109938, 2022). "With substantial progress being made in the field of BCL-2-targeted therapies and our increasing understanding of dysregulation of this family in the myeloid leukemias, great strides have been made in bringing these areas together, as highlighted in this review." (PMID 33637708, 2021). "Consistent with our results, previous studies have shown that probiotics such as L. reuteri 6475 can suppress the ERK1/2 pathway in tumor necrosis factor-treated human myeloid leukemia-derived cells, and that a multispecies probiotic product increased the bcl-2 levels in constipated mice." (PMID 33362802, 2020). "Our mechanistic findings are in contrast to an earlier report, which suggested that in non-solid tumors (myeloid leukemia) Bcl-2 antagonism is synthetically lethal with mutated IDH1 or IDH216." (PMID 29057925, 2017). "For further understand the characteristic of expression and regulation of miR-29 in myeloid leukemia, we searched from miRWalk datebase and found two anti-apoptotic genes Mcl-1 and Bcl-2, which are target genes by both miR-29a and miR-29b and highly correlate to myeloid leukemia." (PMID 25006537, 2014). "It is likely that an early expansion of the MYC-transformed myeloid leukemia cells is counteracted by MYC-induced apoptosis that is overcome by BCL-XL or BCL-2 expression, resulting in an almost immediate tumor transformation of myeloid CD11b/Gr1-positive cells, subsequently causing AML." (PMID 22393362, 2012).
myeloid leukemia (continued). "In the context of human myeloid leukemia, specifically the MOLM13 cell line, prior studies have emphasized the significance of METTL3 in regulating the expression of BCL2, c-Myc, and PTEN." (PMID 40453361, 2024). "In human myeloid leukemia (MOLM13) cells with METTL3 depletion, the level of m6A modification of BCL-2 is reduced, correlating with decreased protein expression." (PMID 39686999, 2024). "Consistent with recent studies, the inhibition of the PI3K/AKT pathway significantly induces antiapoptosis and promotes survival through Mcl-1 and Bcl-2 degradation in AML, human myeloid leukemia cells, and HCC." (PMID 30678274, 2019). "Additionally, m6A has been shown to enhance the translation of c-MYC, BCL2, and PTEN mRNAs in human myeloid leukemia MOLM13 cells." (PMID 40453361, 2024). "Coexpression of MYC and BCL-XL or BCL-2 strongly favored tumor development towards myeloid leukemia, whereas coexpression of MYC and FLIPL did not affect the distribution of myeloid versus lymphoid tumor cells, but changed the ratio between single CD4+ and double positive CD4+CD8+ T-cell lymphomas." (PMID 22393362, 2012). "In contrast to the effects of BCL-XL and BCL-2 overexpression, FLIPL although functional, did not enhance MYC-driven tumorigenesis, neither with respect to the kinetics nor the relative proportion of myeloid leukemia versus T cell lymphoma compared with MYC alone." (PMID 22393362, 2012).
myocardial ischemia (44 papers, 2011 to 2025). A disorder of cardiac function caused by insufficient blood flow to the muscle tissue of the heart. "Additionally, lycopene greatly decreased Bax levels and increased Bcl-2 levels in cardiac injury caused by myocardial ischemia." (PMID 36422550, 2022). "For instance, in animal models with myocardial ischemia/reperfusion (MI/R) injury, a significant upregulation of caspase‐3 and Bax protein expression was observed, along with a decrease in Bcl‐2 expression." (PMID 40551496, 2025). "Bax has been shown to upregulate Bcl-2 expression; conversely, downregulating Bax expression can inhibit apoptosis and alleviate myocardial ischemia." (PMID 40427511, 2025). "The Bax-to-Bcl-2 ratio in the hearts of rats from the CAO group was significantly increased due to myocardial ischemia–reperfusion compared with that in the hearts of rats from the sham group." (PMID 38541636, 2024). "H19 has been reported to perform a function in modulating mitochondrial apoptosis in the process of cardiac ischemia-reperfusion injury via the miR-877-3p/Bcl-2 axis." (PMID 36787444, 2023). "After myocardial ischemia and reperfusion, the expression of Bcl-2 was significantly decreased, the expression of Bax was significantly increased, and apoptosis was increased." (PMID 34765646, 2021). "A recent study demonstrated that TMZ protection against cardiac ischemia/reperfusion injury is dependent on the regulation of the Bcl-2/Bax ratio as Bax facilitates apoptosis while Bcl-2 is an anti-apoptotic protein." (PMID 34220528, 2021). "CircHIPK3 was overexpressed in HCM cells with myocardial ischemia/reperfusion injury, and it up-regulated the expression of Bax and down-regulated the expression of Bcl-2." (PMID 32550826, 2020). "In our WB analyses, renal cortical and myocardial ERK1/2 phosphorylation and Bcl-2 expression were all increased in CKD with cardiac ischemia-reperfusion after linagliptin treatment." (PMID 30823876, 2019). "A recent study demonstrated that TMZ protects against cardiac ischemia/reperfusion injury by augmenting the Bcl-2/Bax ratio." (PMID 30890937, 2019). "miR-29a has been reported to promote cell apoptosis since it promotes the expression of caspase-3 and Bax while reducing Bcl-2 expression in cardiomyocytes after myocardial ischemia-reperfusion." (PMID 31892308, 2019). "Meanwhile, ligustrazine exerts the opposite regulation of Bcl-2, including inhibiting apoptosis in acute myocardial ischemia and neuron cells, triggering apoptosis in cancer." (PMID 31781263, 2019). "Different reports provide evidence showing the participation of bromocriptine, i.e. a D2R agonist, in the down-regulation of caspase 3 activity and the induction of Bcl-2 protein expression in rat cardiomyocytes after myocardial ischemia." (PMID 30427893, 2018). "On the other hand, OSM administration attenuated oxidative stress‐induced cardiac ischemia/reperfusion injury by inhibiting cardiomyocyte apoptosis through upregulating Bcl‐2 expression." (PMID 28297588, 2017). "Our aim was to explore the molecular mechanisms of escitalopram on myocardial apoptosis during myocardial ischemia/reperfusion in a rat model of depression, specifically the expression of Bax and Bcl-2." (PMID 25471226, 2014). "Our aim was therefore to explore the molecular mechanisms of escitalopram on myocardial apoptosis and the expression of Bax and Bcl-2 in a rat model of depression during myocardial ischemia/reperfusion (I/R)." (PMID 25471226, 2014). "According to previous studies, borneol has been shown to alleviate myocardial ischemia–reperfusion injury by reducing the expression of Bax, Bcl-2, and Caspase-3 in cardiomyocytes and to protect neuronal cells by modulating the p38 mitogen-activated protein kinase (MAPK) pathway." (PMID 40872544, 2025).
myocardial ischemia (continued). "The cardioprotection by As‐IV was due to its antiapoptotic effects, indicated by the lowered activity of caspase‐3 and the expression level of Bax and elevation in protein levels of Bcl‐2, which helps it play an important role for preventing cell death during myocardial ischemia." (PMID 40551496, 2025). "In a study of cardiac ischemia reperfusion, Bcl-2 and Bax gene expression were analyzed." (PMID 37909594, 2023). "The shared target genes of hsa-miR-106b and hsa-miR-137, including Bcl-2 and c-Myc, are also involved in cell survival and apoptosis and may contribute to the regulatory network in myocardial ischemia." (PMID 37834231, 2023). "Additionally, TAX attenuated myocardial apoptosis through upregulation of Bcl-2 protein expression and downregulation of protein expression levels of Bax, cytochrome c, and caspase-3 and 9 in a rat model of myocardial ischemia/reperfusion injury." (PMID 36358896, 2022). "Therefore, the balance of Bcl-2 and Bax is an important factor determining the degree of apoptosis in myocardial ischemia reperfusion injury." (PMID 34765646, 2021). "The ensuing finding that APPL1 knockdown led to higher cell apoptosis rates and increased the protein levels of pro-apoptotic-proteins, Bax and cleaved PARP, and reduced anti-apoptosis protein Bcl-2 protein levels that participated in the apoptosis induced by myocardial ischemia/reperfusion." (PMID 34304702, 2021). "Western blotting revealed that TMP increased Bcl-2 and decreased Bax-2 levels, suggesting that TMP-mediated cardioprotection against acute myocardial ischemia injury may occur partially via modulation of Bcl-2 and Bax expression." (PMID 30858867, 2019). "Furthermore, overexpression of eEF2 contributes to the inhibition of cardiomyocyte apoptosis during myocardial ischemia reperfusion via upregulating Bcl-2 expression." (PMID 30987676, 2019). "When Akt is activated, it may cause phosphorylation of Bad or Bax residues, regulating the activity of Bcl-2, thus exerting an antiapoptotic effect during myocardial ischemia." (PMID 30402501, 2018). "The downregulation of miR-497 in response to myocardial ischemia or IR may work as an important adaptive mechanism to upregulate the expression levels of Bcl2 and LC3B." (PMID 26299920, 2015). "The potential mechanisms might be associated with down-regulated expression of TGF-β1, TNF-α, IL-1β, ASK1, NF-κB Bax, up-regulated expression of Bcl-2 and Gata4, activation of eNOS pathway to ameliorate myocardial ischemia, and enhanced cardiac repair." (PMID 24260217, 2013). "Therefore, the Bcl-2:Bax ratio, an index of apoptosis signaling, was significantly reduced in animals subjected to myocardial ischemia in comparison with sham-operated rats and this effect was attenuated by treatment with hemin." (PMID 23592614, 2013). "Their experimental results showed that the highly expressed circHIPK3 in the myocardial ischemia–reperfusion injury model could aggravate myocardial ischemia–reperfusion injury by binding with miR-124-3p, up-regulating pro-apoptotic Bax and down-regulating anti-apoptotic Bcl-2." (PMID 33975598, 2021). "The underlying mechanisms may be via the down-regulation of TNF-α, TGF-β1, IL-1β, Bax, and the up-regulation of Bcl-2, VEGF, Akt and eNOS expression to attenuate myocardial ischemia, enhance neovascularization and cardiac repair." (PMID 31792327, 2019). "As phosphorylation of ERK1/2 and activation of Bcl-2 are important pathways in CKD and MI/R injuries, our data indicate that linagliptin protects the myocardium and renal tubules from CKD with cardiac ischemia-reperfusion induced apoptosis via modulation of the ERK1/2 and Bcl-2 signaling pathways." (PMID 30823876, 2019).
renal carcinoma (44 papers, 2004 to 2025). A carcinoma arising from the epithelium of the renal parenchyma or the renal pelvis. "In addition, CHE treatment decreased the protein level of B‐cell lymphoma‐2 (Bcl‐2) and increased the Bcl‐2 associated X protein (Bax) level in two renal cancer cell lines." (PMID 31568643, 2020). "We have reported that Honokiol-induced renal cancer cell apoptosis is associated with the decreased expression of anti-apoptotic proteins Bcl-2 and Bcl-xL and cytoprotective HO-1; and we checked whether the released Honokiol can modulate the expression of these intracellular molecules." (PMID 33332399, 2020). "It is worth mentioning that previous studies have found that TEK knockdown can significantly promote AKT phosphorylation and inhibit the apoptosis of renal cancer cells by upregulating the downstream pro-apoptotic proteins Bcl-2 and Bcl-xL." (PMID 40808675, 2025). "miR-15a-5p modulates apoptosis through BCL2 targeting and is commonly dysregulated in colorectal and renal cancers." (PMID 41514860, 2025). "Several studies have shown that NF-κB is central to the regulation of BCL-2 in renal cancer cells and nude mouse lung xenografts." (PMID 38062129, 2024). "The data presented here are consistent with the findings of Morais and co-workers, who also demonstrated a decrease in the levels of anti-apoptotic proteins Bcl-2 and Bcl-xL in renal carcinoma cells." (PMID 37511455, 2023). "To investigate the role of apoptosis-related proteins in BMI-1026-induced apoptosis, we used human renal carcinoma Caki cells engineered to overexpress Bcl-2 (Caki/Bcl-2), c-FLIP (L) (Caki/c-FLIP (L)), and Mcl-1 (L) (Caki/Mcl-1 (L))." (PMID 33924053, 2021). "We checked the status of anti-apoptotic marker, Bcl-2 and the cytoprotective ROS scavenger molecule, HO-1 in renal cancer cells following treatments." (PMID 32635337, 2020). "We observed that the released Honokiol significantly downregulated the expression of Bcl-2, Bcl-xL and HO-1 in renal cancer cells (786–0 and ACHN)." (PMID 33332399, 2020). "Our results showed that nobiletin treatment decreased BCL2 expression in renal carcinoma cells, whereas that of BAX was increased." (PMID 31354472, 2019). "As mediated pathway of apoptosis, marked increased PARP and bcl‐2 proteins were seen in urothelial cancer cells while increased caspase‐3 and bcl‐2 were seen in renal cancer cells." (PMID 29953738, 2018). "Recently, the role of As2O3 in renal cancer has also been reported, and As2O3 with amino acids can be used to treat renal cancer by down-regulating Bcl-2 and induce the apoptosis of renal cancer 786-O cells through up-regulating the expression of Bax." (PMID 29633893, 2018). "We have previously reported that c-Met-mediated expression of anti-apoptotic molecules such as Bcl2 and Bcl-xL plays major role in the growth and survival of renal cancer cells." (PMID 28724911, 2017). "The contributions of JNK and Bcl-2 protein phosphorylation to EVO-induced apoptosis of human renal carcinoma cells are still unclear." (PMID 27483435, 2016). "Ectopic expression of Par-4 in renal cancer cells sensitizes TRAIL-resistant Caki cells to apoptosis associated with activation of caspase-8, caspase-3 and modulation of DR5, Bcl-2, Akt, and NF-κB." (PMID 24523904, 2014). "We previously showed that AG490 inhibited STAT3 and induced apoptosis accompanied by the downregulation of Bcl-2 in renal cancer ACHN cells." (PMID 20461084, 2010). "Some in vitro studies have shown that Fas (CD95/Apo1) promotes apoptosis in renal carcinoma cells by immune cells and Bcl-2 prevents it." (PMID 17031406, 2006). "Antihuman Bcl2 antibody was widely distributed all over the renal cancer tissues." (PMID 29104726, 2017).